GCGR (glucagon receptor)
Diseases named in the same sentence as GCGR in open-access papers (continued):
Sharing a sentence is not in itself a finding about the gene and the disease.
tumor (8 papers, 2018 to 2025). "Our study found that GCGR expression was inversely associated with tumour grade, suggesting possible differences in glucagon signalling between early-stage and more advanced tumours." (PMID 40649254, 2025). "This GCGR‐deficient tumor (red curve) regained 5‐FU resistance relative to control tumor treated with 5‐FU plus glucagon (blue curve)." (PMID 38072640, 2024). "Favourable cases, we noted, are marked by THRA-mediated metabolic regulation, RXRG-driven tumour suppression, GCGR-maintained metabolic homeostasis, and FAAH-mediated resolution of inflammation." (PMID 41007296, 2025). "The subversive loop is influenced by glucagon levels in the tumour and organ microenvironment (TOME), as well as the mutational profile and expression levels of the GCGR and GLP-1R." (PMID 40649254, 2025). "Clinically, the high prevalence of GCGR expression in pNET tissues and its inverse correlation with tumour grade, alongside the reduced GLP-1R expression, point to disrupted insulin–glucagon signalling in tumour progression." (PMID 40649254, 2025). "When evaluating the tumour grade, we observed that most grade 1 cases exhibited weak to moderate levels of GCGR, while grade 2 cases showed slightly more intense staining." (PMID 40649254, 2025). "Inhibition of glucagon signaling with the glucagon receptor inhibitor, AL, reversed the glucagon‐enhanced tumor suppression and blood vessel regression." (PMID 38072640, 2024). "In both endothelial and tumor cells, western blot analysis showed that GCGR were remarkably expressed in these cells." (PMID 38072640, 2024). "In the in vivo tumor model, we established a stable glucagon receptor‐knockout CT26 cell line to test its function in tumors." (PMID 38072640, 2024). "We also isolated endothelial cells from CT26 tumor tissues by magnetic‐activated cell sorting, followed by quantitative polymerase chain reaction using mouse GCGR primers." (PMID 38072640, 2024). "Unexpectedly, glucagon did not promote colorectal cell proliferation, although western blotting revealed glucagon receptor expression in tumor cells." (PMID 38072640, 2024). "Histopathological analyses of extracted tumors from mice revealed that tumor cells are prone to be surrounded by stromal tissue in transplanted tumor of GCGR knockdown clones." (PMID 29535833, 2018). "Next, the differences in tumor growth between GCGR knockdown CMT93 clones and control allografts in C57BL/6 and C57BL/6-DIO mice were evaluated." (PMID 29535833, 2018). "Tumor in C57BL/6-DIO mice transplanted GCGR knockdown clones grew significantly slower than in mice transplanted control." (PMID 29535833, 2018). "In summary, this study expands our understanding of glucagon’s role in pNET pathophysiology, emphasizing the significance of metabolic regulation in tumour adaptation and highlighting GCGR as a key candidate for future biomarker development and targeted therapy." (PMID 40649254, 2025). "Our study demonstrates that glucagon, through its interaction with GCGR and/or GLP-1R, plays a pivotal role in orchestrating metabolic and adaptive responses in both tumour and normal endocrine cells, particularly under conditions of glucose deprivation." (PMID 40649254, 2025). "GCGR‐KD tumors showed no changes in tumor growth rate or weight; however, the tumor was not further inhibited on treatment with 5‐FU plus glucagon, compared to 5‐FU treatment alone." (PMID 38072640, 2024). "Furthermore, immunofluorescent staining confirmed that the GCGR was expressed on CT26 and endothelial cells in the tumor tissue." (PMID 38072640, 2024). "Our data show a signaling cascade from extracellular glucagon to nuclear CREB in SNU398 GCGR cells, yet this fails to effectively induce gluconeogenic gene transcription, which we hypothesized would antagonize glycolysis to reduce tumor growth." (PMID 35123542, 2022).
tumor (continued). "We used another GCGR inhibitor, LGD-6972 (LGD), to avoid off-target effects and consistently observed the improvement of tumor-induced wasting in ApcMin/+ mice without affecting tumor growth." (PMID 39924534, 2025).
cancer (7 papers, 2013 to 2025). A tumor composed of atypical neoplastic, often pleomorphic cells that invade other tissues. "The role of glucagon as a cancer regulator, and the usefulness of the GCGR and GLP1-R as biomarkers are underexplored." (PMID 40649254, 2025). "The expression of the GCGR in pNET cell lines and the effects of glucagon on pNET and non-cancer cells were investigated." (PMID 40649254, 2025). "Comparatively, GIPR, which is targeted by dual agonists (e.g., tirzepatide), is expressed in many cancers, while the glucagon receptor (GCGR), which is targeted by triple agonists (e.g., retatrutide), is only detected in a few cancer types." (PMID 41178720, 2025). "Glucagon acts through binding to its receptor, glucagon receptor (GCGR), and cross-talk between GCGR-mediated signals and signaling pathways that regulate cancer cell fate has been unveiled." (PMID 29535833, 2018). "Real-time PCR and western blot analysis demonstrated that GCGR was expressed in seven human cancer cell lines including HT29, SW480, HCT116, CaCO2, T84, WiDr, and COLO205." (PMID 29535833, 2018). "Our findings contribute to filling this gap, demonstrating that glucagon’s interactions with both the GCGR and GLP-1R add complexity to its role in cancer biology, potentially driving adaptive mechanisms in pNET cells." (PMID 40649254, 2025). "Molecular assays showed that glucagon acted as an activator of cancer cell growth through deactivation of AMPK and activation of MAPK in a GCGR-dependent manner." (PMID 29535833, 2018). "Since previous studies in cancer models demonstrated instances of mitochondrial CREB localization, we performed nuclear fractionations on SNU398 eGFP or GCGR cells treated with glucagon to verify if activated p-CREB S133 was spatially capable of facilitating gluconeogenic gene transcription." (PMID 35123542, 2022).
infection (2 papers, 2015 to 2021). The state of being infected such as from the introduction of a foreign agent such as serum, vaccine, antigenic substance or organism. "Altogether, our results demonstrate that GcgR antagonism restores neutrophil migration towards the site of infection, reestablishing local bacterial clearance in diabetic and septic mice." (PMID 34295325, 2021). "Infection efficiency was assessed by immunostaining of GFP in the ARC and decreased protein levels of glucagon receptor in the ARC." (PMID 26909312, 2015).
kidney disease (1 paper, 2024). "Further ongoing kidney disease-focused primary-outcome trials will directly investigate the beneficial effects of dual GLP-1/Glucagon receptor agonists and triple agonists." (PMID 38612779, 2024).
GCGR also shares sentences with these, for which no sentence is quoted: chronic kidney disease (3 papers); cardiovascular diseases (2); heart failure (2); hyperlipidemia (2); neurological disorders (2); acute myeloid leukemia (1); atherosclerosis (1); bacterial infection (1); cardiac hypertrophy (1); Cockayne syndrome (1); colon adenocarcinoma (1); dyslipidaemia (1); endometrial stromal sarcoma (1); Hypercholesterolemia (1); hypercortisolism (1); Hyperinsulinemia (1); hyperuricemia (1); infectious disease (1); liposarcoma (1); lymph node metastasis (1); non-small cell lung carcinoma (1); osteoarthritis (1); Parkinson disease (1); renal cell carcinoma (1); triple-negative breast carcinoma (1).